NPIPB11 (nuclear pore complex interacting protein family member B11)
Synonyms: NPIP
Tractability: Antibody: UniProt predicts a signal peptide or a membrane-spanning region.
Gene: Protein-coding gene on chromosome 16 (29,381,310 to 29,406,711, reverse strand). Ensembl gene ENSG00000254206.
Subcellular location: Membrane
Subcellular location (Human Protein Atlas): Nucleoplasm
Gene Ontology:
Cellular component: membrane
Genetic constraint (gnomAD): Loss-of-function variants: 9 observed, 13.56 expected, observed/expected ratio (o/e) 0.66, 90% interval 0.4 to 1.16. The upper end of that interval is the gene's LOEUF score, 1.16, which puts it in group 5 of 6, group 1 being the genes least tolerant of losing a copy. Missense variants: 406 observed, 451.25 expected, observed/expected ratio (o/e) 0.9, 90% interval 0.83 to 0.98. Synonymous variants: 154 observed, 167.79 expected, observed/expected ratio (o/e) 0.92, 90% interval 0.8 to 1.05.
Homologues: Paralogues in human: NPIPB5 (92% identical), NPIPB4 (88% identical), NPIPB13 (85% identical), NPIPB12 (74% identical), NPIPB3 (32% identical), NPIPB8 (28% identical), NPIPB9 (28% identical), NPIPB6 (27% identical), NPIPB2 (27% identical), NPIPB15 (26% identical), NPIPB7 (25% identical), NPIPA2 (24% identical), and 7 more.
Diseases named in the same sentence as NPIPB11 in open-access papers:
NPIPB11 is named in the same sentence as 5 diseases in open-access papers, as found by Europe PMC text mining. Sharing a sentence is not in itself a finding about the gene and the disease. The quoted sentences say what the papers report.
breast carcinoma (1 paper, 2017). "Little evidence exists for the roles of CHST15 and NPIPB11 in genetic predisposition in familial breast cancer." (PMID 28076423, 2017).
mood disorder (1 paper, 2021). A cognitive disorder a disturbance in which the person's mood is hypothesized to be the main underlying feature. "In the phenome-wide association study, we found seventeen significant gene-trait pairs, including psychosis (NPIPB11, SLX1B) and mood disorders (SCARF2), and overall enrichment of mental traits." (PMID 34715901, 2021).
psychosis (1 paper, 2021). "There were six phenome-wide significant (P < 3.3 × 10−5) gene-trait associations at 16p11.2 including the following: INO80E with skull and face fracture and other intercranial injury (P = 1.9 × 10−15), NPIPB11 with psychosis (P = 1.0 × 10−5), and SLX1B with psychosis (P = 3.0 × 10−5)." (PMID 34715901, 2021).
neurogenetic diseases (1 paper, 2017). "As the examples, copy number change in NBPF10 is associated with multiple developmental and neurogenetic diseases, PABPC3 is involved in regulation of mRNA stability and translation initiation, and NPIPB11 is involved in forming nuclear pore complex." (PMID 28076423, 2017).
NPIPB11 also shares sentences with these, for which no sentence is quoted: cancer (1 paper).